MEIS1 (Meis homeobox 1)
Diseases named in the same sentence as MEIS1 in open-access papers (continued):
Sharing a sentence is not in itself a finding about the gene and the disease.
leukemia (continued). "It has been found that Meis1/Hoxa9 deregulation has an important function in the progression of leukemia." (PMID 33402862, 2020). "MEIS1 along with other homeobox proteins often found to be driving hematopoietic transformation in MLL-rearranged leukemia and described as an oncogene." (PMID 32409701, 2020). "In summary, we have demonstrated that the ability to interact with Crm1 correlates with the recruitment of SQSTM1-NUP214 to Hoxa and Meis1 genes, the activation of their expression, and the induction of leukemias in mice." (PMID 32343715, 2020). "Increased Suv39h1 expression led to the inactivation of Hoxb13 and Six1, as well as reversion of Hoxa9/Meis1 downstream target genes, which in turn decelerated leukemia progression." (PMID 33037410, 2020). "Meis1 was first described in leukemia mouse model and identified as a viral integration site (reviewed in5)." (PMID 32409701, 2020). "They attributed this result, in part, to the repression of the expression levels of DOT1L‐regulated leukemia‐inducing genes, such as MEIS1." (PMID 32526054, 2020). "Next, primary Hoxa9/Meis1 or MLL-AF9 leukemia cells were generated and transplanted to second recipient mice." (PMID 32039742, 2020). "Later, TET1 was verified to promote cell proliferation and induce leukemia by activating the Hoxa9/Meis1/Pbx3 signaling pathway." (PMID 32014008, 2020). "This was directly confirmed by quantitative RT-PCR, whereby we demonstrated that CCI-006, unlike CCI-007, did not decrease the mRNA expression of leukemogenic MLL target genes HOXA9 and MEIS1 in MLL-r leukemia cells." (PMID 30670779, 2019). "This study thus identified a novel small molecule that rapidly kills MLL-rearranged leukemia cells by targeting a metabolic vulnerability in a subset of low HIF1α/low MEIS1-expressing MLL-rearranged leukemia cells." (PMID 30670779, 2019). "It is now postulated that one of the leukemia-driving roles of MEIS1 entails regulating metabolic phenotype through regulating the transcription of HIF1α." (PMID 30670779, 2019). "In conclusion, we have identified a compound that as a single agent selectively kills a subgroup of MLL-r and CALM-AF10 leukemia cells characterized by relatively low-expression levels of HIF1α and MEIS1." (PMID 30670779, 2019). "The intrinsically resistant MLL-r leukemia cells also presented with elevated MEIS1 expression compared to the sensitive cells." (PMID 30670779, 2019). "Further research also indicated that MEIS1 was essential for the development of MLL leukemia, by promoting cell differentiation resistance, and it was also confirmed to be involved in chemotherapy resistance." (PMID 31523525, 2019). "The enhancer E9 mediates an auto-regulatory loop which contributes to the consistent expression of MEIS1 in leukemia." (PMID 31692996, 2019). "A similar trend for a correlation was observed in a smaller MLL-r leukemia patient cohort (n = 21), indicating a possible link between MEIS1 and mitochondrial respiratory chain composition." (PMID 30670779, 2019). "Upon assessing expression levels of MEIS1 in a panel of CCI-006-sensitive and unresponsive cells, the unresponsive MLL-r leukemia cells expressed significantly higher mRNA and protein levels of MEIS1 compared to the sensitive cells." (PMID 30670779, 2019). "Syk signaling then induces Meis1 and thereby recapitulates leukemogenic features of the HoxA9/Meis1 driven leukemia." (PMID 29342970, 2018). "Specifically, oncogenic MLL proteins promote and maintain the overexpression of MEIS1 and HOX cluster genes, triggering the pathological development of MLL-associated leukemia." (PMID 30003105, 2018). "Cells with this immunophenotype are enriched for leukemia-initiating activity in Hoxa9/Meis1 murine leukemias." (PMID 29346763, 2018).
leukemia (continued). "Recent genome-wide ChIP-seq analyses identified various sets of direct target genes of MLL-FP, which consistently included the master regulatory factors (HOXA7, HOXA9, HOXA10, and MEIS1) required for the development of MLLr-leukemias." (PMID 29692408, 2018). "It was shown to be an efficient inhibitor of MLL1 activity leading to a reduction of the expression of MLL1 target genes, such as HoxA9 and Meis1, in leukemia cell lines." (PMID 28182322, 2017). "When transplanted into irradiated recipient mice, cells transduced with Hoxa9 (H) or Hoxa9/Meis1 (H/M) gave rise to leukemia resulting in a median overall survival of 114 and 41 days, respectively (p < 0.001)." (PMID 28399410, 2017). "Leukemias induced by the combination of Hoxa9 with hSYK or Hoxa9 with Meis1 were characterized by lower leukocyte counts and a more pronounced anemia compared with Hoxa9 alone." (PMID 28399410, 2017). "Our orthogonal treatment results, based on both shRNA-mediated knockdown and pharmacological inhibition of Syk, showed that Hoxa9/Meis1-transformed leukemias were clearly more sensitive to Syk inhibition than Hoxa9-transformed leukemias." (PMID 28399410, 2017). "In the context of Hoxa9 overexpression, Syk signaling induces Meis1, recapitulating several leukemogenic features of Hoxa9/Meis1-driven leukemia." (PMID 28399410, 2017). "Treatment with these MLLi led to down-regulation of gene-expression programs enforced by MLL fusion, such as HOXA9 and MEIS1, in the leukemia cells." (PMID 29075615, 2017). "Investigations into the dependence of MLL-r leukemias on upregulation of these genes have shown that MEIS1 is necessary for leukemia growth and proliferation and that levels of expression of MEIS1 correlate inversely with disease latency." (PMID 28232907, 2017). "For example, miR-196b can target either tumour suppressor, FAS or oncogene, HOXA9/MEIS1 in leukaemia." (PMID 28458781, 2017). "We found that the combination of Hoxa9 and hSYK significantly increased the aggressiveness of the leukemias compared with Hoxa9 alone (median of 38.5 versus 103.5 days; p < 0.001), with a median survival remarkably similar to that of Hoxa9/Meis1 (39 days)." (PMID 28399410, 2017). "The DOT1L protein is essential for the growth of MLL-rearranged leukemia cells and exerts its effect by maintaining active transcription of Hoxa9 and Meis1." (PMID 28231254, 2017). "MN1 is also a potent and sufficient oncogene in murine leukemia models, strongly dependent on the MEIS1/AbdB-like HOX protein complex to transform common myeloid progenitors, block myeloid differentiation, and promote leukemic stem cell self-renewal." (PMID 28960191, 2017). "This leads to aberrant H3K79 methylation at MLL target gene loci, causing dysregulated gene expression (e.g., overexpression of HoxA9 and Meis1) and eventually initiation of the leukemia." (PMID 26970896, 2016). "Leading edge Gene Set Enrichment Analysis (GSEA;) of all differentially expressed genes showed enrichment in cell cycle genes in MxCre/Meis1-/- LSK cells, consistent with the loss of quiescence seen in other studies and leukemia models." (PMID 26986211, 2016). "MLL-r leukemia cells that were resistant to the compound were characterised by significantly higher baseline gene expression levels of MEIS1 and BCL2 in comparison to CCI-007 sensitive MLL-r leukemia cells." (PMID 27317766, 2016). "Indirect evidence for a role of a hyperactivated HOXA9/MEIS1 pathway in MLL-r leukemia also comes forward from several gene expression studies in patients with MLL-r leukemia." (PMID 27317766, 2016). "Although the functions of all resultant fusion proteins have not been fully characterized, some commonalities exist, such as the up-regulation of downstream genes, Hoxa9 and Meis1, which in combination can induce aggressive leukemia in recipient mice." (PMID 27007052, 2016).
leukemia (continued). "More biological studies demonstrated that LSD1 inhibitors 1 and 2 were able to downregulate the expression of leukemia-relevant genes HoxA9 and Meis1, induce apoptosis, and differentiation." (PMID 26970896, 2016). "Conversely, recent study has been reported that GSK-3 promotes the association of CREB and its co-activators with MEIS1, a homeobox (HOX) DNA-binding cofactor, to induce HOX-mediated transcription and transformation in MLL leukemias." (PMID 27049759, 2016). "Since it is well known that MEIS1 and HOXB6 synergistically cooperate in leukemia induction, the detection of MEIS1/HOXB6 combination among the leukemic mice further validates the usefulness of the current model system." (PMID 26606454, 2015). "We previously screened RE-IIBP target genes in leukemia cell line and reported that the transcription of MEIS1 is regulated by RE-IIBP17." (PMID 26206755, 2015). "Increasing of HOX transcriptional activity by MEIS1 is known to contribute to accelerated development of leukemia." (PMID 26206755, 2015). "In primary hematopoietic progenitors, Meis1 overexpression is unable on its own to transform, but cooperates in the oncogenic activity by accelerating HoxA9-induced leukemia." (PMID 24809472, 2014). "It remains to be established why the Prep1i/i-dependent aggressiveness of Meis1-HoxA9 leukemia appears only at a later stage." (PMID 24809472, 2014). "Previous studies have shown that Meis1 plays an important role in blood development and vascular homeostasis, and can induce blood cancers, such as leukemia." (PMID 25013928, 2014). "In contrast to the established role of Meis1 in leukemia development, its function in postnatal hematopoiesis, especially in HSCs as well as hematopoietic progenitor cells (HPCs), remains uncertain." (PMID 24498346, 2014). "We show that, Meis1 on its own is unable to induce leukemia in primary fetal liver (FL) cells hypomorphic for Prep1 expression (Prep1i/i)." (PMID 24809472, 2014). "Meis1 is often co-ordinately over-expressed in various leukemias with its transcriptional partners the TALE domain protein Pbx1 and one or more homeodomain containing Hox family members, and collaborates with them in accelerating leukemogenesis." (PMID 23308270, 2013). "Strikingly, MEIS1 is a highly expressed oncogene in leukemia, and its downregulation is a marker that indicates a good prognosis." (PMID 24244575, 2013). "Although high expression promotes leukemia cell proliferation, silencing of MEIS1 increases resistance to the chemotherapeutic etoposide, in agreement with our findings in IMR32 cells." (PMID 23442791, 2013). "An earlier study showed DOT1L to be essential for HOXA9 and MEIS1 expression and the resulting leukemia driven by MLL-AF9." (PMID 23847761, 2013). "Using Flt3 knock out mice, we previously found that leukemias induced by the retroviral transduction of Hoxa9 and Meis1, which recapitulate many features of MLL-rearranged myeloid leukemias, are Flt3 independent." (PMID 23977266, 2013). "Human leukemias with MLL rearrangements are strongly correlated with expression of the MEIS1 and HOXA9 genes." (PMID 24213472, 2012). "In acute myeloid leukemia, miR-204 targets HOXA10 and MEIS1, two members of the homeobox family of transcription factors involved in leukemia development." (PMID 20302635, 2010). "Two probes for MEIS1 gene (204969_at, 15559477_s_at), which encodes a cofactor for HOX proteins that can accelerate Hoxa9-dependent leukemia, were shown to be strongly expressed in MLL positive samples, as previously reported." (PMID 19549311, 2009). "Our results confirm the primary function of MEIS1 gene in regulating fundamental MLL leukemia-related and HOX genes processes." (PMID 19549311, 2009). "HOXA9 is frequently induced in human AML with poor prognosis and Hoxa9 can induce leukemia in murine BM transplantation models in collaboration with Meis1 similar to what we have shown for ND13 and NA10." (PMID 17712416, 2007).
leukemia (continued). "Experimental interference with the dimerisation between PBX3 and MEIS1 resulted in destabilisation of MEIS1 and a significant decline in HoxA9-induced proliferation and colony formation in primary cells and animal models of leukemia." (PMID 41535654, 2026). "If the activation of this cell‐fate program is blunted by genetic or epigenetic mechanisms, leukemia cells may become resistant to the Menin inhibitor despite its retained ability to silence HOXA/MEIS1 gene expression programs." (PMID 39887730, 2026). "Importantly, forced expression of Hoxa9 in combination with the co‐factors Meis1 or Pbx3 alone was sufficient to induce leukemia, establishing those genes as central functional drivers in KMT2A‐rearranged leukemia by shaping the leukemic enhancer landscape." (PMID 39887730, 2026). "Cell line/primary blasts/in vivo (THP-1, U937, ER-HoxA9 GMP Cell Lines, the HoxA9 + Meis1 or MLL/AF9 primary leukemia cells.Subcutaneous xenograft tumor mice models, disseminated intravenous xenograft leukemia mice models, patient AML sample engrafted (PDX) mice)." (PMID 41590345, 2026). "Gene editing studies have shown that NPM1 mutant leukemias are dependent on menin and MEIS1 for their leukemogenic function, and knocking out these genes disrupts the menin-HOX-MEIS1 axis that leads to differentiation, loss of proliferation, and impaired leukemogenesis." (PMID 39594699, 2024). "While the non‐mutated NUP98::HOXA9 fusion protein bound to genes associated with developmental processes and leukemia, inducing HOX genes, PBX3 and MEIS1 in the context of regions decorated with the activating H3K27ac histone mark, this pattern was lost when the NUP98 N‐terminal IDR was mutated." (PMID 39323480, 2024). "In leukemia patients with NPM1c, or rearrangements in KMT2A and NUP98, a number of these regulators are considered instrumental for loss of transcriptional control and aberrant expression of HOXA/B/MEIS1, and other leukemia-associated target genes." (PMID 38174649, 2023). "Meis1 gene is not only involved in cell proliferation and differentiation, but also actively involved in blood vessel development and hematopoiesis, and its malfunctioning closely related to leukemia." (PMID 36952432, 2023). "Therefore, the leukemia-driving abilities of Meis1 are at least partly due to a low OS, supported by HLF." (PMID 36139768, 2022). "Identifying the transcriptional regulators of MEIS1 with the long-term goal of identifying ways to alter MEIS1 expression could be beneficial for developing new therapies in MEIS1-dependent leukemias." (PMID 35624144, 2022). "We next turned our focus to early leukemia progression in a Hoxa9/Meis1-Ubiquitin-c-GFP (HA9M1) mouse model of AML, performing intravital imaging of the calvarium bone marrow between 1 and 3 days after transplanting 3 × 106 cells into non-irradiated recipients." (PMID 36424441, 2022). "We identified differential methylation of genes that have been related to cancers such as lymphoma (WNT6, TP73, and CD37), leukaemia (MEIS1, HOXA4, and HOXA5) or neuroblastoma (TP73), as well as genes related to cardiovascular diseases (UCN, PRDM16, TCAP, ALOX5)." (PMID 35354948, 2022). "The leukemia cells expressed posterior Hox genes, Meis1, c-Kit, and Myc." (PMID 36335100, 2022). "All three Meis1 leukemia models show a strong Meis1 peak at the same position of the Fli1 locus." (PMID 35624144, 2022). "In addition, there was evidence showing that miR-17 ~ 92 cluster contributed to the MEIS1/HOXA9-mediated transformation of MLL leukemia." (PMID 35536524, 2022). "The results displayed that Meis1 is relevant for progress of established leukemia." (PMID 36139768, 2022). "Thus, additional MYC activation mediated by MLL fusions and MEIS1 confers proliferative advantages sufficient to induce leukemia in vivo." (PMID 34310280, 2021).
leukemia (continued). "Representative PCR gel results revealed three specific bands corresponding to HoxB5, HoxA9, and Meis1, indicating that these driving oncogenes were gnomically integrated into the leukemia cells and suggesting their involvement in leukemia generated in ML23 mice." (PMID 33602907, 2021). "Probe intensities of HOXA9 and MEIS1 are plotted separately by leukemia phenotype (ALL or AML) (B)." (PMID 34310280, 2021). "It is well established that HOXA9 and MEIS1 overexpression drives leukemogenesis in MLL-r leukemia." (PMID 34698191, 2021). "When overexpressed in murine hematopoietic progenitors, MN1 causes an aggressive AML characterized by an aberrant myeloid precursor-like gene expression program that shares features of KMT2A-rearranged (KMT2A-r) leukemia, including high levels of Hoxa and Meis1 gene expression." (PMID 33542482, 2021). "Viral co-transduction of the MLL-AF4 targets HOXA9 and MEIS1 is sufficient to cause acute leukemia in mouse bone marrow progenitors, arguing that these transcription factors represent a major etiologic pathway in MLL-r leukemia." (PMID 34263728, 2021). "Indeed, we observed a significant decrease in Meis1 and Hoxa9 expression in Δ10-DOT1L and I867A-DOT1L leukemia cells, comparable to the changes induced by complete loss of DOT1L (empty vector) or by DOT1L enzymatic inhibition (RCR-DOT1L)." (PMID 33562706, 2021). "To date, two menin-MLL1 inhibitors (K0539, NCT04067336 and SNDX-5613, NCT04065399) have demonstrated preclinical activity in HOXA/MEIS1 genes-driven leukemias, including MLL-r and NPM1-mutant AML, and have entered clinical testing with a focus on patients with MLL-rearrangements or NPM1 mutations." (PMID 34698191, 2021). "NPMc+ and IDH2R140Q together activate the Hoxa9/Meis1 pathway to drive leukemia in mice." (PMID 34944812, 2021). "The trimeric structure of HOXA9/MEIS1/PBX3 supports HOXA9-driven leukemia." (PMID 33402862, 2020). "MEIS1 and MEIS2 interact with HOX and PBX variants in leukemia." (PMID 33402862, 2020). "Moreover, enforced expression of TGIF1 in MLL‐AF9‐transduced leukaemia cells influences transcriptional networks regulated by MEIS1, another TALE family member, while the TGIF1:MEIS1 ratio predicts AML survival." (PMID 33058427, 2020). "Given that SQSTM1-NUP214 was identified in a leukemia with upregulation of HOXA genes, we examined the effect of SQSTM1-NUP214 on transcript levels of Hoxa and Meis1, an essential Hox cofactor, in the bone marrow blasts of murine leukemias induced by SQSTM1-NUP214." (PMID 32343715, 2020). "Meis1 has been identified as one of the primary factors in the formation of leukemia." (PMID 33402862, 2020). "The presence of PBX3 and MEIS1 increases HOXA9-induced leukemia." (PMID 33402862, 2020). "Herein, we demonstrate that Suv39h1 is significantly down-regulated in AMLs and could function as a tumor suppressor in MLL-rearrangement induced leukemia by regulating Hoxb13 and Six1, as well as Hoxa/Meis1 downstream signature genes." (PMID 33037410, 2020). "In addition, unresponsive MLL-rearranged leukemia cells expressed increased levels of MEIS1, an important leukemogenic MLL target gene that plays a role in regulating metabolic phenotype through HIF1α." (PMID 30670779, 2019). "If MEIS1 potentiates the leukemia action of HOXA9, this is also the case of PBX3, whose expression is also strongly correlated with HOXA9 expression, especially in leukemia subtypes with a normal karyotype or associated with MLL rearrangements." (PMID 31213012, 2019). "Furthermore, HOXA9 and MEIS1 have been reported as target genes of oncogenic MLL-AF9 fusion proteins in human leukemia." (PMID 30003105, 2018). "In addition, it was also shown to reduce the expression of MLL1 target genes such as HoxA9 and Meis1 in leukemia cell lines." (PMID 28182322, 2017).